TRBV4-2 (T cell receptor beta variable 4-2)
Description:
V region of the variable domain of T cell receptor (TR) beta chain that participates in the antigen recognition. Alpha-beta T cell receptors are antigen specific receptors which are essential to the immune response and are present on the cell surface of T lymphocytes. Recognize peptide-major histocompatibility (MH) (pMH) complexes that are displayed by antigen presenting cells (APC), a prerequisite for efficient T cell adaptive immunity against pathogens. Binding of alpha-beta TR to pMH complex initiates TR-CD3 clustering on the cell surface and intracellular activation of LCK that phosphorylates the ITAM motifs of CD3G, CD3D, CD3E and CD247 enabling the recruitment of ZAP70. In turn ZAP70 phosphorylates LAT, which recruits numerous signaling molecules to form the LAT signalosome. The LAT signalosome propagates signal branching to three major signaling pathways, the calcium, the mitogen-activated protein kinase (MAPK) kinase and the nuclear factor NF-kappa-B (NF-kB) pathways, leading to the mobilization of transcription factors that are critical for gene expression and essential for T cell growth and differentiation. The T cell repertoire is generated in the thymus, by V-(D)-J rearrangement. This repertoire is then shaped by intrathymic selection events to generate a peripheral T cell pool of self-MH restricted, non-autoaggressive T cells. Post-thymic interaction of alpha-beta TR with the pMH complexes shapes TR structural and functional avidity.
Synonyms: TCRBV7S3A2; TCRBV7S3A2T; TRBV42; TCRBV4S2
Tractability: Antibody: UniProt places it where antibodies can reach, with medium confidence; UniProt predicts a signal peptide or a membrane-spanning region; its Gene Ontology location is reachable by antibodies, with medium confidence.
Gene: T-cell receptor variable (V) gene on chromosome 7 (142,345,421 to 142,345,985, forward strand). Ensembl gene ENSG00000211745.
Subcellular location: Cell membrane
Gene Ontology:
Biological process: cell surface receptor signaling pathway
Cellular component: plasma membrane
Homologues: Orthologues: mouse Trbv5 (63% identical). Paralogues in human: TRBV4-1 (83% identical), TRBV3-1 (61% identical), TRBV5-1 (43% identical), TRBV23-1 (42% identical), TRBV5-4 (42% identical), TRBV9 (42% identical), TRBV12-5 (41% identical), TRBV18 (40% identical), TRBV7-1 (40% identical), TRBV12-4 (39% identical), TRBV5-5 (39% identical), TRBV7-2 (39% identical), and 39 more.
Diseases named in the same sentence as TRBV4-2 in open-access papers:
TRBV4-2 is named in the same sentence as 2 diseases in open-access papers, as found by Europe PMC text mining. Sharing a sentence is not in itself a finding about the gene and the disease. The quoted sentences say what the papers report.
narcolepsy (2 papers, 2021 to 2023). A sleep disorder characterized by a tendency for excessive sleepiness during the day which occurs even after adequate sleep in the nighttime. "One TCR (TCR165) from one patient but also another TCR (TCR173) from one healthy donor reactive against RFX4-86 used TRBV4-2, which has been strongly implicated in narcolepsy pathophysiology by our lab before through genetic analysis." (PMID 33837283, 2021). "A logical explanation for this observation could be that a TCR-mediated reactivity that involves receptors containing TRAJ24F, TRAJ28 and TRBV4-2 is an important step in the development of narcolepsy, perhaps through TCR recognition of a viral trigger or an autoantigen by CD4+ or CD8+ cells." (PMID 37188663, 2023).
TRBV4-2 also shares sentences with these, for which no sentence is quoted: influenza (1 paper).